NOS3 (nitric oxide synthase 3)
Diseases named in the same sentence as NOS3 in open-access papers (continued):
Sharing a sentence is not in itself a finding about the gene and the disease.
Cholestatic liver disease (1 paper, 2016). "The harmful effects of bile acid accumulation occurring during cholestatic liver diseases have been associated with oxidative stress increase and endothelial nitric oxide synthase (NOS-3) expression decrease in liver cells." (PMID 27490694, 2016). "AP-1 appears as a potential therapeutic target in cholestatic liver diseases given its role as a transcriptional repressor of NOS-3." (PMID 27490694, 2016).
congenital heart disease (1 paper, 2013). A heart disease that is present at birth. "Other studies have shown that an increased risk of congenital heart disease, especially conotruncal heart defects, is associated via a reduction in the NOS3 activity induced by a common 894G > T single nucleotide polymorphism." (PMID 23742172, 2013).
disseminated candidiasis (1 paper, 2019). Systemic candidiasis occurs when Candida yeast enters the bloodstream and may spread (becoming disseminated candidiasis) to other organs, including the central nervous system, kidneys, liver, bones, muscles, joints, spleen, or eyes. "Collectively, these data demonstrate that Nos3-/- mice are more resistant to disseminated candidiasis and specifically associated with reduced renal pathology." (PMID 31671151, 2019). "Our finding that iNOS induced locally in kidneys of Nos3-/- mice is associated with protection against disseminated candidiasis may have translational applications." (PMID 31671151, 2019). "IL-9 is a pro-inflammatory cytokine derived from Th-9 cells that was consistently elevated based on our intracellular flow data and on day 4 PI in serum from infected Nos3-/- mice, suggesting it contributes to protection against disseminated candidiasis." (PMID 31671151, 2019). "NOS3/eNOS is expressed by endothelial cells in the kidney, and colonization of this organ was decreased during the sub-acute stage of disseminated candidiasis." (PMID 31671151, 2019). "Although absolute numbers were not determined, the increased relative abundance of Th2 and Th9 CD4+ cells in spleens of infected Nos3-/- mice suggest that these T helper subsets enhance protective immunity, and their role in human disseminated candidiasis merits further investigation." (PMID 31671151, 2019).
functional dyspepsia (1 paper, 2022). "The increased IL1B, TNFT, RPV1, and NOS3 expression in the duodenum of functional dyspepsia model mice were significantly affected following BHM treatment, suggesting that BHM regulates duodenum functionality and reduces inflammatory response by targeting these genes." (PMID 35668782, 2022). "Isorupestonic acid has the maximum binding energy with NOS3 (−9.10 kcal/mol), which may play a significant role in the effect of isorupestonic acid on functional dyspepsia." (PMID 35668782, 2022). "In the present study, it is shown that BHM may play a critical role in treating functional dyspepsia via regulating IL1B, TNF, TRPV1, SERT, and NOS3 signaling pathways." (PMID 35668782, 2022).
fungal keratitis (1 paper, 2017). "The average ratios of the expression levels of the Hmox1, Nos3, Hif1a, Sod2, Sod3, and Gpx2 genes increased more than 2-fold (p < 0.05) at day 1 p.i. in the fungal keratitis model, whereas the expression ratios of the Hif1an and Prdx6 genes decreased more than 2-fold (p < 0.05)." (PMID 28874754, 2017).
gastrointestinal bleeding (1 paper, 2021). "Logistic regression model for genetic variants in PTGS1 and NOS3 genes in low-dose aspirin and nonsteroidal anti-inflammatory drug users, and risk of upper gastrointestinal bleeding secondary to complicated peptic disease." (PMID 34290607, 2021).
gastroschisis (1 paper, 2024). Gastroschisis is marked by viscera protruding, without a covering sac, from the fetal abdomen on the right lateral base of the umbilicus. "Padula investigated 75 genetic variants in 20 genes and found 11 gastroschisis-associated variants in NOS3, ADD1, GNB3, ICAM1, ICAM4, ICAM5, and NAT1 genes." (PMID 39728087, 2024). "Besides ICAM1, the study from the Torfs group also identified a heterozygous/homozygous variant of NOS3, NPPA, ADD1, SERPINE1, and SELE, genes involved with cell–cell interactions, inflammation, or blood pressure, associated with gastroschisis." (PMID 39728087, 2024).
glomerulonephritis (1 paper, 2013). A renal disorder characterized by damage in the glomeruli. "When 12 and 16 week old mice in the Schoeb study were examined, there was a trend to greater glomerulonephritis in the NOS3−/− mice." (PMID 23741359, 2013).
HELLP syndrome (1 paper, 2015). A life-threatening condition that can potentially complicate pregnancy. "Complementary chi-square analysis of the subgroup of preeclamptic women showed that, in a recessive model, NOS3 T-786C was significantly associated with the occurrence of either HELLP syndrome or eclampsia (P<0.0001)." (PMID 26317342, 2015). "The presence of at least one polymorphic allele for NOS3 T-786C was also associated with the occurrence of eclampsia or HELLP syndrome among preeclamptic women." (PMID 26317342, 2015).
hepatoblastoma (1 paper, 2015). Hepatoblastoma (HB) is a malignant hepatic tumor and is the most common pediatric liver cancer.
hypertensive nephropathy (1 paper, 2022). Kidney damage that results from chronically elevated blood pressure; complications include glomerular damage resulting in proteinuria and hematuria. "We found that ApoE/NOS3−/− mice reproduced normally, had a blood pressure of 133.00 ± 3.85 mmHg, and developed hypertensive fundus retinopathy and hypertensive nephropathy." (PMID 36360235, 2022). "ApoE/NOS3−/− mice had features of hypertensive nephropathy and hypertensive retinopathy." (PMID 36360235, 2022).
hypotension (1 paper, 2017). "In previous studies, we found an endothelial nitric oxide synthase gene (NOS3) variant rs2070744 associated with the ambulatory blood pressure (BP) response following bouts of moderate and vigorous intensity acute exercise, termed post‐exercise hypotension (PEH)." (PMID 29180482, 2017).
leukoaraiosis (1 paper, 2022). "Homozygosity for this NOS3 (endothelial NOS) variant has been shown to increase the risk of leukoaraiosis by 290%." (PMID 35517054, 2022).
limb ischemia (1 paper, 2012). A ischemia that involves the limb. "Statins activate endothelial Akt, which results in phosphorylation of NOS3 and enhanced angiogenesis in a model of limb ischemia." (PMID 23144940, 2012).
lupus nephritis (1 paper, 2013). Glomerulonephritis in the context of systemic lupus erythematosus. "This suggests that NOS3-derived NO modulated MCP1 production in the setting of lupus nephritis." (PMID 23741359, 2013).
metastatic melanoma (1 paper, 2021). A melanoma that has spread from its primary site to another anatomic site. "Analysis of Riker gene array with 87 samples from Oncomine showed high NOS3 expression in metastatic melanoma when compared to the primary site (GSE7553)." (PMID 34502464, 2021). "Since reduced Nos3 expression, as well as L-sepiapterin treatment in 4C11+ metastatic melanoma cells, induced restoration of its activity by increasing NO synthesis and decreasing O2−•, cell survival was evaluated." (PMID 34502464, 2021). "Finally, NOS3 expression was found to be increased in human metastatic melanoma samples compared with the primary site." (PMID 34502464, 2021). "Therefore, increased Nos3 expression could be a result of altered redox homeostasis found in 4C11+ metastatic melanoma cells." (PMID 34502464, 2021).
moyamoya angiopathy (1 paper, 2023). "Moreover, the recent finding of biallelic NOS3 variants in familial moyamoya angiopathy underlines the importance of the NO pathways and warrants future functional exploration of the consequences of the variants identified." (PMID 37383439, 2023).
myocardial disorder (1 paper, 2025). A disorder that affects the muscle tissue of the heart. "It was established that the NOS3*C minor allele of the 786T>C (rs2070744) polymorphism of the NOS3 gene can be an additional risk factor for age- associated electrophysiological myocardial disorders in men living in extreme northern conditions." (PMID 41426971, 2025).
pancreatic adenocarcinoma (1 paper, 2021). "Tumor tissues with the highest NOS3 expression were STAD (9.85 ± 1.018), kidney renal clear cell carcinoma (KIRC, 9.848 ± 0.9791), pancreatic adenocarcinoma (PAAD, 9.297 ± 0.8167)." (PMID 33747912, 2021).
pancreatic ductal adenocarcinoma (1 paper, 2021). An infiltrating adenocarcinoma that arises from the epithelial cells of the pancreas. "Upregulation of Nos3 expression has been associated with K-Ras-driven tumors, as pancreatic ductal adenocarcinoma and papillomas, since NO, through wild-type Ras S-nitrosylation, activates this signaling pathway, leading to tumor growth." (PMID 34502464, 2021).
pancreatitis (1 paper, 2021). Inflammation of the pancreas. "In order to further explore the relationship between the results of this experiment and human AP, we analyzed the expression of three key genes TNF, NOS3, and TGFB1 in human pancreatitis tissues." (PMID 34925503, 2021).
pneumococcal pneumonia (1 paper, 2014). A febrile disease caused by STREPTOCOCCUS PNEUMONIAE. "Pharmacologic targeting of NOS3 with one type of drug already in clinical use (statins) and another small-molecule lead compound (AVE3085) led to improved bacterial clearance and improved survival from secondary pneumococcal pneumonia." (PMID 25317947, 2014).
pneumonitis (1 paper, 2010). An inflammatory process affecting the lung parenchyma. "In contrast, genetic variation in NOS3 was associated with a 50% decrease in pneumonitis risk (HR:0.55, 95% CI:0.31–0.96)." (PMID 20811626, 2010). "This variant, rs1799983, in NOS3 was associated with a 70% reduction in risk of pneumonitis." (PMID 20811626, 2010).
prostate adenocarcinoma (1 paper, 2022). "The expression of CSF1 and all 3 NOS isoforms (NOS3, NOS2, and NOS1) were evaluated using RNA sequencing data for Prostate adenocarcinoma from The Cancer Genome Atlas (TCGA)." (PMID 36209194, 2022).
renal hypertension (1 paper, 2016). Hypertension caused by the kidney's hormonal response to narrowing or occlusion of the renal arteries. "Seven of them (Agtr1a, Fn1, Gja1, Lama2, Mmp2, Mmp9, Nos3) are known as being associated with renal hypertension." (PMID 28105926, 2016). "The changes in expression of DEGs associated with renal hypertension (Agtr1a, Fn1, Gja1, Lama2, Mmp2, Mmp9, Nos3) may also be suggested to have a significant impact on disease development in ISIAH rats." (PMID 28105926, 2016).
respiratory failure (1 paper, 2025). The significant impairment of gas exchange within the lungs resulting in hypoxia, hypercarbia, or both, to the extent that organ tissue perfusion is severely compromised. "In experimental models, NOS3 deficiency leads to profound lung abnormalities, respiratory failure, and early mortality, highlighting its role in pulmonary development, although its specific contribution to neonatal RDS remains incompletely defined." (PMID 40941746, 2025).
skin toxicity (1 paper, 2019). "We also investigated the relationship between ANGPT2 and NOS3 polymorphisms and the main toxicities (skin toxicity, asthenia, and diarrhea)." (PMID 31330833, 2019). "We found also that NOS3 rs1799983 was associated with late skin toxicity (p = 0.021) and with a higher grade (CTCAE 4.0) of this toxicity (p = 0.003)." (PMID 31330833, 2019).
thrombophilia (1 paper, 2024). A condition characterized by an abnormally high level of thrombi. "For instance, IL-10 polymorphism, RAAS, FOXP3, thrombophilia, and NOS3 were found to be associated with an increased risk of PE." (PMID 39194706, 2024).
thyroid (1 paper, 2025). "Future research should investigate NOS3 gene expression and epigenetic regulation in patients with DTC to uncover potential mechanisms of NO involvement in thyroid tumorigenesis." (PMID 39859471, 2025).
thyroid cancer (1 paper, 2025). "This suggests a potential difference in how NOS3 polymorphisms affect different thyroid cancer subtypes, considering that we investigated these polymorphisms in more than just the papillary subtype of thyroid cancer." (PMID 39859471, 2025). "Further research should investigate the interaction of NOS3 gene polymorphisms with other molecular markers involved in the oncogenesis of thyroid cancer." (PMID 39859471, 2025). "Furthermore, as our study was cross-sectional, it is limited in establishing causal relationships between these NOS3 polymorphisms and thyroid cancer outcomes." (PMID 39859471, 2025). "Resources such as the International Cancer Genome Consortium (ICGC) and the Genotype-Tissue Expression (GTEx) project could help explore the associations between NOS3 polymorphisms, gene expression, and thyroid cancer phenotypes." (PMID 39859471, 2025). "Furthermore, it is possible that epigenetic modifications of the NOS3 gene could impact thyroid cancer risk, considering the recent studies that showed a complex relation between epigenetic modifications and thyroid cancer." (PMID 39859471, 2025). "These approaches would provide greater statistical power and broader insights into the role of NOS3 in thyroid cancer biology." (PMID 39859471, 2025). "The relationship between NOS3 gene polymorphisms and thyroid cancer has not been clearly established, with only a limited number of studies conducted in this area." (PMID 39859471, 2025). "In the absence of experimental studies directly investigating the role of NOS3 in thyroid cancer, future research could involve murine models and CRISPR-Cas9 gene editing technologies to explore the functional implications of NOS3 gene polymorphisms." (PMID 39859471, 2025). "The TCGA-THCA dataset, which includes whole-genome and whole-exome sequencing data from a large cohort of patients with thyroid cancer, mainly PTC, offers an opportunity to assess the prevalence and clinical relevance of NOS3 polymorphisms, such as rs1799983 and rs2070744." (PMID 39859471, 2025). "Finally, our study did not explore the potential interactions between NOS3 polymorphisms and other molecular markers involved in thyroid cancer pathogenesis." (PMID 39859471, 2025). "Nevertheless, it remains possible that NOS3-mediated NO production influences thyroid cancer oncogenesis via different pathways that were not explained by the polymorphisms examined in our study." (PMID 39859471, 2025).
ureteric obstruction (1 paper, 2013). "In unilateral ureteric obstruction (UUO) we observed an acute (6 hr) down-regulation of nitric oxide synthase 3 (NOS3/eNOS) levels and increased phosphorylation of the linker region of Smad3 at T179 and S208 in Smad3/JNK complexes." (PMID 24391884, 2013).
uveal melanoma (1 paper, 2021). A melanoma derived from melanocytes of the uveal tract. "Tumor tissues with the lowest NOS3 expression were LAML (5.071 ± 1.591), kidney renal papillary cell carcinoma (KIRP, 7.173 ± 1.14), uveal melanoma (UVM, 7.278 ± 0.9764)." (PMID 33747912, 2021).
vascular malformation (1 paper, 2009). A non-neoplastic disorder that is the result of defects of vascular morphogenesis. "Coherent with this notion, NOS3, the enzyme required for constitutive NO formation in ECs has been shown to be downregulated in ECs harvested from HHT patients, a pathology due to heterozygous mutations in either endoglin or Alk1 and characterized by multiple vascular malformations." (PMID 19340291, 2009).
vasculitis (1 paper, 2013). "For instance, focal hypercellularity, necrosis, crescents, chronic inflammation, tubular casts, and vasculitis scores were significantly greater in NOS3−/− compared to NOS3+/+ controls." (PMID 23741359, 2013).
viral infections (1 paper, 2024). "The role of NOS3 in the production of nitric oxide (NO) has emerged as a pivotal factor in host defense against viral infections." (PMID 39600882, 2024).
cardiovascular disease (77 papers, 2007 to 2026). "The substitution of a T with a cytosine (C) is associated with reduced NOS3 transcription, which results in lower NO production, potentially leading to an increased risk of cardiovascular disease and cancer progression." (PMID 41528397, 2026). "A link has also been found between Pb and endothelial nitric oxide synthase gene (NOS3), correlating with susceptibility to cardiovascular disease." (PMID 41614871, 2025). "The NOS3 gene has been linked to various cancers and cardiovascular diseases due to its role in NO synthesis and the regulation of vascular tone." (PMID 39859471, 2025). "NOS3 is a unique NO synthase in vascular endothelial cells, and NOS3 polymorphisms are related to the susceptibility of individuals to cardiovascular diseases." (PMID 38802855, 2024). "For some DNB genes, NOS3 polymorphisms are associated with the progression of kidney and cardiovascular disease in Type 2 diabetic patients." (PMID 36141135, 2022). "Among EC-derived factors, endothelial nitric oxide synthase NOS (eNOS, NOS3)-produced NO release is fundamental to vascular homeostasis as disruption of NO production leads to endothelial dysfunction and underlies cardiovascular disease." (PMID 34222255, 2021). "Homozygotes (AA carriers) of the NOS3 SNP rs1799983 (also known as Glu298Asp) A minor allele have increased risk of cardiovascular diseases." (PMID 29703528, 2018). "The synergic effect of NOS3 (eNOS) Asp298 allele confirms its pathological role for cardiovascular diseases in T2DM patients." (PMID 28761062, 2017). "It had been proved that the NOS3 polymorphism (rs1799983) was associated with the development of cardiovascular diseases." (PMID 23922896, 2013). "The T-786C polymorphism in the promoter region of NOS3 has also been repeatedly associated with cardiovascular disease." (PMID 22919264, 2012). "However, some authors have associated the (-786T>C + -786T>C) genotype with low levels of NOS3 mRNA, which would be contributing to a higher risk of cardiovascular diseases." (PMID 18823560, 2008). "Furthermore, in other conditions in which NO fulfils a regulatory role, such as in cardiovascular diseases in general or in metabolic disorders, genotyping the NOS3 polymorphism could be clinically relevant." (PMID 41528397, 2026). "NOS3, etc., controlled cardiovascular disease pathways, and HRAS, etc., played a key role in hormone signalling networks." (PMID 41155650, 2025). "Inflammation and cardiovascular disease are associated with expressions of ANP, cTnT, NOS3, MMP-9, and IL-6 genes." (PMID 38348351, 2023). "Understanding the cellular pathways that regulate endothelial nitric oxide (eNOS, NOS3) expression and consequently nitric oxide (NO) bioavailability during hypoxia is a necessary aspect in the development of novel treatments for cardiovascular disorders." (PMID 28536619, 2016). "While many associations are not consistently noted from study to study, a review of the available studies reveals a modest overall association of clinical cardiovascular disease or SCA with variants in candidate genes, such as APOE, ACE, and NOS3." (PMID 17903303, 2007). "Polymorphic loci of four genes whose products are involved in blood pressure control (ACE, BDKRB2, NOS3 and PPARGC1A) can be used in martial arts not only to determine predisposition to cardiovascular disease but also to predispose to the development of speed and power qualities and endurance." (PMID 36140844, 2022). "This included NOS3 mRNA quantification, genotyping of an intronic putative non-coding RNA (ncRNA) locus suspicious for pathomechanistic relevance in cardiovascular diseases, monitoring of CpG signalling at the NOS3 promoter and quantification of PTMs relevant for chromatin structure regulation." (PMID 25699114, 2015). "Nitric oxide synthase 3 (NOS3) catalyzes production of NO in the endothelium and may play a role in cardiovascular disease (CVD)." (PMID 22470539, 2012).